ATP6AP1L (ATPase H+ transporting accessory protein 1 like (pseudogene))
Synonyms: ATP6AP1LP
Gene: Transcribed unitary pseudogene on chromosome 5 (82,295,449 to 82,318,300, forward strand). Ensembl gene ENSG00000205464.
Subcellular location: Membrane
Diseases named in the same sentence as ATP6AP1L in open-access papers:
ATP6AP1L is named in the same sentence as 4 diseases in open-access papers, as found by Europe PMC text mining. Sharing a sentence is not in itself a finding about the gene and the disease. The quoted sentences say what the papers report.
breast carcinoma (4 papers, 2018 to 2025). "Then, we cloned the ATP6AP1L (ATPase H + Transporting Accessory Protein 1 Like), a gene mediating breast cancer predisposition of rs10514231, into the two vectors under CMV promoter/enhancer and transfected K-562 cells." (PMID 36250010, 2022). "TWAS (transcriptome-wide association study) analysis identified that the ATP6AP1L gene was significantly associated with breast cancer risk." (PMID 34359652, 2021). "Here, we revealed that rs10514231 affects breast cancer risk by altering ATP6AP1L expression through a functional interaction with TCF7L2." (PMID 34359652, 2021). "Notably, ATP6AP1L downregulation correlated with breast cancer risk and with poor prognosis in patients." (PMID 34359652, 2021). "We have recently found that ATP6AP1L overexpression in breast cancer cells suppressed cell proliferation." (PMID 36250010, 2022). "Our further systematic mechanical study focusing on the rs10514231 site revealed that the variation affected ATP6AP1L gene expression by altering the chromatin binding of TCF7L2 to the therein regulatory element and led to breast cancer susceptibility." (PMID 34359652, 2021). "Further investigation into the mechanism of ATP6AP1L in breast cancer will provide additional insight into the etiology of breast cancer." (PMID 34359652, 2021). "Notably, we found that the ATP6AP1L expression level was significantly lower in the basal-like and Her2+ breast cancer samples than in normal samples." (PMID 34359652, 2021). "It suggests that the ATP6AP1L gene might function as a suppressor in breast cancer progression, except for the LumB subtype breast cancer." (PMID 34359652, 2021). "Our study observed attenuated expression of ATP6AP1L in the basal-like and Her2+ subtypes of the breast cancer samples compared to normal breast tissues and a shorter recurrence-free survival time with the lower expression group in most subtypes of breast cancer patients." (PMID 34359652, 2021). "In-depth studies, such as tumor xenograft experiments, might be demanded to thoroughly investigate the roles of the ATP6AP1L gene in breast cancer before being translated into clinics." (PMID 34359652, 2021). "Consistently, our experiments validated that ATP6AP1L overexpression inhibited breast cancer cell proliferation and migration, suggesting that ATP6AP1L might play a tumor-suppressor role in breast cancer progression." (PMID 34359652, 2021). "We next investigated the clinical impact of ATP6AP1L expression on breast cancer progression." (PMID 34359652, 2021). "A major remaining question will be how ATP6AP1L influenced breast cancer." (PMID 34359652, 2021). "Five of these were strong cross-tissue eQTLs in GTEx (for ATG10, ATP6AP1L, and RPS23, all associated with rs7707921, and C5orf35 (also known as SETD9) and rs889312; P < 1 × 10− 5 in at least 19 tissues with concordant directionality) and maintain their regulatory capacity in breast cancer cells." (PMID 30205839, 2018).
proctitis (1 paper, 2022). An inflammatory process affecting the anus. "The ATP6AP1L gene has been reported to be associated with proctitis." (PMID 36250010, 2022).
cancer (1 paper, 2021). A tumor composed of atypical neoplastic, often pleomorphic cells that invade other tissues. "Overexpression of the ATP6AP1L gene in cancer cells diminished cell proliferation, migration, and invasion." (PMID 34359652, 2021). "The colony-forming assay also showed that ATP6AP1L overexpression significantly impeded the cancer cells’ ability to survive and form colonies in MDA-MB-453 and MDA-MB-468 cells, and ATP6AP1L overexpression showed the same impact in T47D cells despite no significance." (PMID 34359652, 2021).
ATP6AP1L also shares sentences with these, for which no sentence is quoted: tumor (1 paper).